MGMT (O-6-methylguanine-DNA methyltransferase)
Diseases named in the same sentence as MGMT in open-access papers (continued):
Sharing a sentence is not in itself a finding about the gene and the disease.
glioma (1,330 papers, 2003 to 2026). A benign or malignant brain and spinal cord tumor that arises from glial cells (astrocytes, oligodendrocytes, ependymal cells). "METHODS: We utilized the Cas13x and Cas13d variants to target MGMT mRNA in the MGMT-expressing LN18 glioma cell line and in two patient-derived gliomasphere lines (GS104, GS081)." (PMID 41817895, 2026). "Specifically, QX302 exhibited significant anticancer efficacy against MGMT-overexpressing glioma T98G and MMR-deficient colorectal carcinoma HCT116 cell lines." (PMID 41513607, 2026). "ADC value can be used as a noninvasive predictor of MGMT promoter methylation status in IDH wild-type glioma, and the relative ADC value further enhances the diagnostic stability." (PMID 40958862, 2025). "The mechanisms underlying TMZ resistance are multifactorial and include MGMT overexpression, activation of glioma stem cells, and metabolic dysregulation." (PMID 41244832, 2025). "Several studies showcased the effectiveness of radiomics and/or deep learning (DL) techniques in predicting IDH mutation, MGMT promoter methylation, and survival status of glioma patients." (PMID 41561752, 2025). "MGMT promoter methylation serves as a prognostic marker associated with longer patient survival in gliomas but lacks predictive value for response to PCV specifically." (PMID 41375081, 2025). "Previous studies have reported that MGMT promoter methylation is associated with higher rates of distant glioma recurrence." (PMID 40705330, 2025). "ATRX loss and OLIG2 overexpression support glioma stemness and chromatin remodeling, while MGMT activity influences chemoresistance." (PMID 40282990, 2025). "Since the majority of IDHmut gliomas have methylation-induced suppression of the gene encoding the DNA repair enzyme O-6-Methylguanine-DNA Methyltransferase (MGMT), the DNA alkylating agent temozolomide (TMZ) is a mainstay of therapy in these tumors." (PMID 41066183, 2025). "The activity of KL-50 was maintained in cell-derived xenograft glioma models in which it displayed effective tumor control in MGMT-silenced tumors with loss of MMR that were impervious to TMZ." (PMID 41169667, 2025). "In gliomas, O6-methylguanine-DNA methyltransferase (MGMT) status has been associated with ICI resistance." (PMID 41211067, 2025). "Often patients with H3 G34-mutant glioma have MGMT promoter methylation which is associated with a better response to alkylating therapies, such as TMZ7,9." (PMID 40813437, 2025). "Here, we specified two initial centroids of mass, the IDH mutant type/MGMT promoter methylated samples and IDH wild type/MGMT promoter unmethylated samples, because of the strong association between IDH mutation and MGMT promoter methylation in gliomas." (PMID 40757022, 2025). "Using a different strategy, our group sought to develop an improved therapy that would maintain the selectivity for MGMT silenced gliomas, but overcome resistance driven by loss of MMR86." (PMID 41169667, 2025). "Multivariate Cox regression analysis further demonstrated that age, pathological grade, IDH, and MGMT remained as independent risk factors for glioma prognosis (P < 0.05)." (PMID 40860684, 2025). "We proposed a multitask CA-EfficientNetV2 model based on MR imaging for the simultaneous prediction of IDH mutation and MGMT promoter methylation in gliomas." (PMID 40757022, 2025). "As per IDH mutation, SWI represents a valuable tool in differentiating MGMT promoter mutations in gliomas." (PMID 40870498, 2025). "Methylation of the MGMT promoter leading to loss of MGMT expression occurs in approximately half of GBMs and 70–80% of anaplastic and low-grade gliomas." (PMID 41169667, 2025). "The O6-methylguanine-DNA methyltransferase (MGMT) promoter methylation is associated with a higher degree of survival in high-grade glioma, partly due to better treatment response to alkylating agents." (PMID 40560010, 2025).
glioma (continued). "Currently, isocitrate dehydrogenase (IDH) and O6-methylguanine-DNA methyltransferase (MGMT) are the most common molecular biomarkers associated with glioma progression and prognosis." (PMID 40860684, 2025). "Despite the strong associations between several factors—such as IDH mutation status, 1p19q codeletion, and MGMT promoter methylation—and survival in glioma, accurate prognostic markers remain elusive." (PMID 39901195, 2025). "The probability of the high‐risk group in MGMT promoter unmethylation gliomas was also significantly higher compared to methylation gliomas, which is consistent with previous conclusions, indicating the accuracy of the SVM‐based subtyping of the TCGA cohort." (PMID 40264576, 2025). "In recent years, mutated IDH1 and MGMT promoter methylation were the most common research targets in gliomas and they were associated with longer OS and PFS." (PMID 39049072, 2024). "Upon comparing IDH mutation status with MGMT methylation, we found a significant difference in proportion; most of the MGMT-unmethylated gliomas were also IDH-wild type (p < 0.001)." (PMID 38167551, 2024). "Preclinical combination therapies involving ATRi were investigated with temozolomide in O6-methylguanine-DNA methyltransferase (MGMT)-deficient glioma cells as well as with the oncolytic CAN-2409/Ganciclovir system." (PMID 38475864, 2024). "The combination of IDH mutation status and MGMT promoter methylation provides even more valuable information for predicting prognosis and guiding treatment decisions in glioma patients." (PMID 39100020, 2024). "Predicting IDH mutation status and MGMT promoter methylation in glioma patients is of significant clinical importance as these molecular markers play a crucial role in determining prognosis and guiding treatment decisions." (PMID 39100020, 2024). "IDH-mutant gliomas with MGMT promoter methylation have been associated with a more favorable prognosis compared to IDH-wildtype gliomas with MGMT promoter methylation." (PMID 39100020, 2024). "Methylation of this gene’s promoter leads to a decreased synthesis of the MGMT enzyme and has been independently associated with increased survival in infiltrating gliomas, including GBMs, as a result of an increased response to temozolomide." (PMID 39273661, 2024). "Through RNA sequencing data analysis, we evaluated the relationship between GSN expression levels, IDH mutations, and MGMT methylation status in glioma obtained from the CGGA database." (PMID 38803199, 2024). "1p/19q gene deletion, IDH gene mutation and MGMT gene promoter methylation have been widely studied and identified as diagnostic and predictive markers for glioma typing and tumor progression." (PMID 39075190, 2024). "In clinical practice, IDH mutation status, 1p/19q co-deletion status, and MGMT promoter methylation status are of significant importance in predicting prognosis, treatment response, and clinical management of gliomas." (PMID 39211050, 2024). "In particular, the number of patients in the sub-analyses on IDH mutation status and MGMT methylation status was limited and the glioma group included both patients with primary glioma and those with tumor recurrence." (PMID 39227460, 2024). "Loss of O6-methylguanine-DNA-methyltransferase(MGMT) protein expression due to promoter methylation reduces glioma cell DNA repair activity and resistance to alkylating agents." (PMID 39760063, 2023). "Among the cancer genes associated with dDMRs, we found that MGMT dDMR methylation in low-grade glioma was associated with response to JQ1 (BET inhibitor, dDMR calling, adj." (PMID 37558831, 2023). "In glioma, the methylation status of the O6-methylguanine-DNA methyltransferase (MGMT) promotor is associated with the response to temozolomide treatment." (PMID 36762114, 2023).
glioma (continued). "Prime causes of this are a fast progression of the tumor and the resistance to temozolomide caused by expression of O6-methylguanine-DNA methyltransferase (MGMT) reversing the changes in DNA caused by the drug, which occurs in most cases of high-grade gliomas." (PMID 36831260, 2023). "In gliomas, promoter methylation of the DNA repair gene O^6-methylguanine-DNA methyltransferase (MGMT) is associated with increased TMZ responsiveness." (PMID 37444408, 2023). "High tumor purity, 1p19q co-deletion, IDH mutation, and MGMT promoter methylation are all good prognostic factors for glioma." (PMID 37501725, 2023). "Simple linear regression showed that MGMT promoter methylation pyrosequencing scores positively correlated with driver mutation VAF among all gliomas (slope = 24.8, R2 = 0.040, p < 0.0001)." (PMID 37919784, 2023). "We found that in the training group, expression of the TARDBP gene, PRS type, age, IDH mutation status, 1p/19q codeletion status, WHO grade and MGMT status significantly correlated with glioma patients’ OS." (PMID 37147573, 2023). "Previous studies have used 1p/19q chromosomal codeletion, mutations of IDH1/2, and MGMT promoter methylation as three molecular biomarkers to guide the classification and treatment decisions of glioma." (PMID 37837543, 2023). "The analysis of MGMT methylation is of paramount importance for gliomas, as it occurs in more than half of IDH-mutated astrocytomas and in about half of IDH wild-type glioblastomas." (PMID 37626776, 2023). "Methylation of MGMT promoter region leads to loss of expression of MGMT protein causing a reduction in the DNA repair activity of glioma cells and thus prevents their resistance to temozolomide." (PMID 39760063, 2023). "By pyrosequencing, 56% of all gliomas with driver mutation VAF ≥ 0.325 had MGMT promoter methylation, versus only 37% with VAF < 0.325 (p < 0.0001)." (PMID 37919784, 2023). "Biomarkers of response to standard of care in gliomas remain extremely limited, with MGMT promoter methylation and IDH mutation status as the only predictive biomarkers currently in clinical use in malignant gliomas." (PMID 37916170, 2023). "According to another prognostic analysis, GFAP expression and MGMT promoter methylation were linked to the survival prognosis of patients with glioma." (PMID 37090987, 2023). "Second, some key molecular alterations, such as IDH mutation and O6‐methylguanine‐DNA methyltransferase (MGMT) promoter methylation, have been shown to affect glioma location predilection." (PMID 36305649, 2023). "In our risk model, glioma patients with MGMT promoter methylation, 1p19q codeletion, and IDH mutation presented a relatively lower risk score, suggesting a better prognosis." (PMID 37004060, 2023). "The unmethylated MGMT promoter was detected in 50% of gliomas and is known to cause cells to be insensitive to alkylating chemotherapy." (PMID 37416766, 2023). "Hypermethylation of the MGMT promoter results in gene silencing; therefore, gliomas with methylated MGMT promoters are more susceptible to the effects of alkylating agent therapy, such as temozolomide." (PMID 37754483, 2023). "Mutant IDH1 and O6-methylguanine DNA methyltransferase (MGMT) promoter methylation associate with well prognostic outcomes of glioma patients." (PMID 38027011, 2023). "The heatmap showed that Nature-killer cell gene expression was correlated with WHO grade, IDH1 mutation, MGMT promoter methylation, 1p19q co-deletion, tumor subtype in glioma patients in CGGA and TCGA datasets." (PMID 35236310, 2022). "Risk scores were evaluated for each glioma patient (risk score = CLSPN*0.734 + MGMT*0.28 + POLN*0.3 + SFN*0.187)." (PMID 36092717, 2022). "A nomogram comprising gender, age, grade, IDH1 mutation, MGMT status, pq status, and risk score was created to predict OS in glioma tissues." (PMID 35903107, 2022).
glioma (continued). "Consistently, metabolic cluster 1 was associated more with IDH wild type, 1p/19q non‐co‐deletion, MGMT un‐methylated, and CL/ME subtypes of gliomas." (PMID 36134697, 2022). "In this manuscript, we have sought to systemically characterize the relative impact of unique MMR mutations in the setting of MGMT-proficient and -deficient glioma cells." (PMID 35388070, 2022). "The fact that more than 90 % of IDH-mutant gliomas exhibit a hypermethylated MGMT profile is an excellent indication that in these cases the MGMT epigenetic alteration is a consequence of IDH mutations and 2-HG accumulation." (PMID 36361838, 2022). "For example, promoter methylation of MGMT was found in approximately 40% of GBMs, and inactivation of the MGMT is associated with the clinical response to alkylating agents in glioma patients." (PMID 34894053, 2022). "If the MGMT promoter is methylated, it will cause the loss of MGMT expression, resulting in a decrease in DNA repair and making gliomas more sensitive to chemotherapy drugs such as TMZ." (PMID 36614997, 2022). "Several studies have used direct ADC values to predict IDH mutation or MGMT promoter methylation status of gliomas, and the area under the curve (AUC) varied from 0.686 to 0.870." (PMID 36711137, 2022). "Among the numerous biomarkers, only IDH mutations, MGMT promoter methylation, and 1p19q codeletion are being routinely used in clinic diagnosis for glioma patients, while other biomarkers are still in observation phage in clinical trials." (PMID 35338570, 2022). "We sought to recapitulate the MMR deficiency phenotype observed in the LN229 MGMT- cells using another glioma cell line." (PMID 35388070, 2022). "If the MGMT promoter is methylated, it will cause the loss of MGMT expression, resulting in a decrease in DNA repair and making gliomas more sensitive to chemotherapy drugs such as temozolomide (TMZ)." (PMID 35807084, 2022). "Totally, isocitrate dehydrogenase (IDH) mutation tests were performed in 108 glioma specimens; 98 specimens underwent MGMT promoter methylation measurements; 74 specimens had 1p/19q codeletion analysis." (PMID 35968285, 2022). "Molecular characteristics such as IDH mutation status and MGMT methylation status have been used for pathological diagnosis of glioma." (PMID 35936006, 2022). "In ~40% of gliomas, the expression of the MGMT gene is silenced due to epigenetic hypermethylation of CpG islands in its promoter region, leading to the loss of MGMT expression and increased sensitivity towards alkylating agents." (PMID 35365623, 2022). "IDH mutation and the MGMT promoter methylation have been included as critical prognostic molecular markers for glioma." (PMID 35214183, 2022). "Machine learning approaches allow the classification of individual genetic mutations of gliomas, and the prediction of MGMT promoter methylation was also realized through deep learning algorithms." (PMID 35743511, 2022). "The result supported that lipoic acid exerts detrimental effects on glioma cells as hypomethylation of MGMT is directly associated with the high resistance toward temozolomide chemotherapy treatment." (PMID 36557318, 2022). "Molecular features, such as isocitrate dehydrogenase (IDH) mutations, TERT promoter mutations, MGMT promoter methylation, and chromosome 1p/19q co-deletion status, have been found to serve as indicators for glioma prognosis and classifications." (PMID 35874989, 2022). "Purpose and background: Isocitrate dehydrogenase (IDH) mutation and O-6 methyl guanine methyl transferase (MGMT) methylation are surrogate biomarkers of improved survival in gliomas." (PMID 36675733, 2022). "There have obtained many identifications about some phenotypes of glioma which are useful to prognosis, such as methylation of the MGMT, mutations in IDH1/2 and so on." (PMID 35931979, 2022).
glioma (continued). "Subsequently, gender, age, grade, IDH mutation, MGMT methylation and risk were included to build a nomogram predicting 1‐, 3‐ and 5‐year survival of glioma patients." (PMID 36317420, 2022). "Serum miR-4297 levels were positively associated with MGMT protein expressions in female glioma specimens (p = 0.014)." (PMID 35968285, 2022). "The present research suggests that IDH1 mutation, 1p19q LOH, EGFR mutation and MGMT promoter methylation are newly added major molecular markers for genetic molecular typing of glioma." (PMID 36181110, 2022). "The clinicopathological characteristics of glioma correlate with prognosis, so we analyzed the risk scores of gliomas in different subtypes compartmentalized by different grade, gender, age, MGMT status, 1p/19q status, and IDH status." (PMID 35592707, 2022). "It was reported that the methylation of the MGMT gene promoter is associated with glioma prognosis and recurrence." (PMID 34131250, 2021). "It is well-known that several molecular biomarkers, such as isocitrate dehydrogenase (IDH) mutation, 1p/19q codeletion status and O6-methylguanine DNA methyltransferase (MGMT) promoter methylation are related to the malignancy of gliomas." (PMID 33664747, 2021). "The associations between expression quantitative trait loci (eQTLs) of MGMT and glioma susceptibility were evaluated in a case–control study of 1056 individuals." (PMID 34544433, 2021). "Specially, glioma‐associated NHAs were reported to protect MGMT‐negative glioma cells from TMZ‐induced apoptosis by the functional intercellular transfer of exosomal MGMT mRNA." (PMID 33609076, 2021). "By contrast, the diagnostic accuracy of TBR/ADC was not significantly higher than that of single ADC or 18F-FET PET for gliomas with 1p/19q codeletion, MGMT promoter methylation and PTEN mutation." (PMID 34912706, 2021). "The methylation of the CpG island of the MGMT enzyme promoter is associated with better survival of patients with high grade gliomas that are given alkylating agents as chemotherapy." (PMID 33680961, 2021). "We demonstrated that an eQTL of MGMT rs11016798 was significantly associated with glioma susceptibility." (PMID 34544433, 2021). "More to the point, a consistent trend was observed in all 4 tag-eQTLs that subjects carrying the genotypes associated with higher MGMT expression were more likely to have decreased risk of developing glioma." (PMID 34544433, 2021). "Important factors associated with the prognosis of high-grade gliomas included age, extent of resection, number of gliomas, and MGMT methylation status." (PMID 35096561, 2021). "We also explored that the risk score was lower in IDH mutation, 1p19q codel and MGMT methylated significantly which were the clinical features with good prognosis of glioma." (PMID 34123852, 2021). "We collected the clinicopathological characteristics of these patients, including gender, age at diagnosis, disease staging, KPS score of glioma patients, MGMT promoter methylation and IDH mutation." (PMID 33663509, 2021). "Robust biomarkers such as IDH mutation and MGMT promoter methylation are associated with better survival in gliomas." (PMID 34439271, 2021). "In the present study, we conducted a case–control study consisting of 402 glioma patients and 654 controls to investigate the associations of the eQTLs of MGMT with glioma susceptibility." (PMID 34544433, 2021). "In terms of CTV, the ME of glioma is related to tumor grade and MGMT methylation, IDH mutation and 1p/19q co-deletion status." (PMID 34784919, 2021). "Several studies have correlated multimodal MRI (T1, T2, FLAIR, and T1C) with glioma MGMT mutation status." (PMID 34676470, 2021).